APOBEC3D (apolipoprotein B mRNA editing enzyme catalytic subunit 3D)
Description:
DNA deaminase (cytidine deaminase) which acts as an inhibitor of retrovirus replication and retrotransposon mobility via deaminase-dependent and -independent mechanisms. Exhibits antiviral activity against HIV-1. After the penetration of retroviral nucleocapsids into target cells of infection and the initiation of reverse transcription, it can induce the conversion of cytosine to uracil in the minus-sense single-strand viral DNA, leading to G-to-A hypermutations in the subsequent plus-strand viral DNA. The resultant detrimental levels of mutations in the proviral genome, along with a deamination-independent mechanism that works prior to the proviral integration, together exert efficient antiretroviral effects in infected target cells. Selectively targets single-stranded DNA and does not deaminate double-stranded DNA or single- or double-stranded RNA. Also inhibits the mobility of LTR and non-LTR retrotransposons. (Microbial infection) Enhances hepatitis B virus/HBV replication by excluding restriction factors APOBEC3F and APOBEC3G from HBV capsids.
Synonyms: A3D; A3DE; APOBEC3DE; ARP6; APOBEC3E
Tractability: PROTAC: ubiquitination databases record sites on it.
Gene: Protein-coding gene on chromosome 22 (39,021,113 to 39,033,277, forward strand). Ensembl gene ENSG00000243811.
Subcellular location: Cytoplasm; Cytoplasm, P-body
Gene Ontology:
Molecular function: cytidine deaminase activity; RNA binding; hydrolase activity; zinc ion binding
Biological process: clearance of foreign intracellular DNA; defense response to virus; DNA cytosine deamination; negative regulation of single stranded viral RNA replication via double stranded DNA intermediate; cytidine to uridine editing
Cellular component: cytoplasm; P-body; nucleus
Genetic constraint (gnomAD): Loss-of-function variants: 37 observed, 47.31 expected, observed/expected ratio (o/e) 0.78, 90% interval 0.6 to 1.03. The upper end of that interval is the gene's LOEUF score, 1.03, which puts it in group 4 of 6, group 1 being the genes least tolerant of losing a copy. Missense variants: 496 observed, 509.24 expected, observed/expected ratio (o/e) 0.97, 90% interval 0.9 to 1.05. Synonymous variants: 175 observed, 184.15 expected, observed/expected ratio (o/e) 0.95, 90% interval 0.84 to 1.08.
Homologues: Orthologues: chimpanzee APOBEC3D (88% identical). Paralogues in human: APOBEC3F (77% identical), APOBEC3B (60% identical), APOBEC3G (41% identical), APOBEC3C (38% identical), APOBEC3A (20% identical), AICDA (18% identical), APOBEC2 (16% identical), APOBEC3H (16% identical), APOBEC1 (15% identical).
Diseases named in the same sentence as APOBEC3D in open-access papers:
APOBEC3D is named in the same sentence as 11 diseases in open-access papers, as found by Europe PMC text mining. Sharing a sentence is not in itself a finding about the gene and the disease. The quoted sentences say what the papers report.
breast carcinoma (4 papers, 2015 to 2025). "Our results with APOBEC3D likely indicate a parallel with APOBEC3B in breast cancer, a mutagenic activity of APOBEC3D in CRCs, and suggest survival benefit with a specific inhibitor of APOBEC3D." (PMID 35817785, 2022). "While for other APOBEC members, including APOBEC3D, APOBEC3F, and APOBEC3G, they show DNA hyper-methylation in ER− breast cancer cells when compared to HMEC (P < 0.01, Wilcoxon signed rank test)." (PMID 26682542, 2015). "For other APOBEC family members, they show either extremely low (median log2-transformed RPKM < 0) mRNA levels (including APOBEC3A, APOBEC3H, APOBEC1, APOBEC2, APOBEC4, and AICDA), or no obvious expression differences between ER+ and ER− breast cancers (including APOBEC3D, APOBEC3F, and APOBEC3G)." (PMID 26682542, 2015).
viral infection (4 papers, 2015 to 2016). "Despite the increased activity of chimpanzee APOBEC3D relative to the human protein, the Vif protein from two divergent SIVcpz isolates was able to antagonize chimpanzee APOBEC3D and to rescue viral infection (black bars)." (PMID 26394054, 2015).
COVID-19 (3 papers, 2022 to 2024). A disease caused by infection with severe acute respiratory syndrome coronavirus 2. "We found a high expression of APOBEC3A, APOBEC3B, APOBEC3C, APOBEC3D, APOBEC3F, APOBEC3G and APOBEC3H in the classical, intermediate monocytes and NK cells of the COVID-19 patients compared to the healthy or recovered individuals." (PMID 36532041, 2022). "Genes in this pathway, AICDA, CDADC1, CDA and APOBEC3D, were regulated in opposite directions (only AICDA was statistically significantly downregulated in SLE and CDA up in COVID-19), while APOBEC3A and APOBEC3B were significantly upregulated in COVID-19, but not SLE." (PMID 38302132, 2024).
cervical cancer (1 paper, 2020). A primary or metastatic malignant neoplasm involving the cervix. "We found that the LOXL2-interference resulted in an increase in APOBEC3A, APOBEC3B, APOBEC3D, and APOBEC3G protein levels in the cervical cancer cells." (PMID 32211324, 2020). "Therefore, we also integrated the APOBEC family (APOBEC1 APOBEC3A, APOBEC3B, APOBEC3C, APOBEC3D, APOBEC3F, APOBEC3G, and APOBEC3H) mRNA expression of 176 core-set cervical carcinoma samples for multiplatform integrative analyses." (PMID 32211324, 2020).
colon tumors (1 paper, 2021). "However, our data show that certain APOBECs (e.g. APOBEC3A, APOBEC3C, APOBEC3D, etc.)are highly expressed in CYT-high colon tumors, providing evidence of their involvement in them." (PMID 34316699, 2021).
HIV-1 infection (1 paper, 2014). The type species of lentivirus and the etiologic agent of acquired immunodeficiency syndrome (AIDS). "Consistent with a previous study in CD4+ T cell cultures in vitro, WT HIV-1 infection significantly enhanced the mRNA expression of APOBEC3D, APOBEC3F, and APOBEC3G." (PMID 25330146, 2014).
cancer (6 papers, 2017 to 2022). A tumor composed of atypical neoplastic, often pleomorphic cells that invade other tissues. "To further explore ADAR1-driven RNA editing events, we performed RESSq-PCR analysis on other cancer-associated loci, including the DNA cytidine deaminase APOBEC3D, antizyme inhibitor 1 (AZIN1), and murine double minute 2 E3 ubiquitin protein ligase (MDM2)." (PMID 29203771, 2017). "Together, either IL-6 exposure or continuous lenalidomide treatment enhanced A-to-I editing of GLI1 as well as other cancer-associated associated transcripts, including APOBEC3D, AZIN1, and MDM2." (PMID 29203771, 2017). "Furthermore, APOBEC3F and APOBEC3D appear to change in specific cancer environments, such as UCEC; missense mutation is the main form in all mutation events." (PMID 34638749, 2021). "It has been reported that the expression of APOBEC3D, TNFRSF14, and RAC2 is dysregulated and is a potential target for therapy in cancer." (PMID 36059808, 2022).
tumor (6 papers, 2018 to 2025). "Accordingly, we found upregulation of APOBEC family genes (APOBEC3B, APOBEC3D and APOBECC3G) in IR type tumours compared with that in other types." (PMID 32235905, 2020). "Conversely, the TreeSHAP model considered CIAPIN1 to be a non-contributory gene and instead highlighted APOBEC3D, which is known to drive tumor resistance." (PMID 41020875, 2025).
infection (5 papers, 2014 to 2023). The state of being infected such as from the introduction of a foreign agent such as serum, vaccine, antigenic substance or organism. "Moreover, in vitro single-round infection assays revealed that the mutation signatures of APOBEC3D, APOBEC3F, and APOBEC3G were GA-to-AA, GAA-to-AAA, and TGGG-to-TAGG, respectively." (PMID 25330146, 2014).
APOBEC3D also shares sentences with these, for which no sentence is quoted: clear cell renal cell carcinoma (1 paper); colorectal tumors (1).